CRP (C-reactive protein)
Diseases named in the same sentence as CRP in open-access papers (continued):
Sharing a sentence is not in itself a finding about the gene and the disease.
bladder cancer (continued). "The aim of this study was to investigate the changes of values and analysis of differences between the determined parameters of oxidative stress (TAS-s and TAS-f, MDA, AOPP), angiogenesis (ANG) and inflammation (CRP) in blood plasma/serum of patients with bladder cancer and the control group." (PMID 30828780, 2020). "The levels of these two glycan features were correlated to C-reactive protein concentration, an inflammation marker and known prognostic indicator for bladder cancer, further strengthening the link between inflammation and abnormal plasma protein glycosylation." (PMID 30040854, 2018). "In addition CRP predicted prognosis in most reports in other solid tumors, so it may also be a clinically useful predictor in lung, pancreas, hepatocellular, and bladder cancers." (PMID 26717416, 2015). "The serum concentrations of CRP, CEA, CA19-9, and GSDM D according to the sex of the tested patients (a total of patients with bladder cancer and healthy individuals) were also evaluated." (PMID 39766111, 2024). "CRP, a constituent element of GPS, is one of the most well-known prognostic factors in urothelial carcinomas including bladder cancer and UTUC." (PMID 29348903, 2017). "C-reactive protein (CRP), which is an acute-phase reactant and a useful marker of systemic inflammation, has been shown to be a biomarker for bladder cancer." (PMID 26014498, 2015). "Additionally, the median of GSDM D concentration was notably elevated in LG and HG bladder cancer than in C. In the total study group, the GSDM D concentration correlated with CRP and CEA levels." (PMID 39766111, 2024). "The objective of this study is to assess the significance of preoperative C-NLR, a new inflammation-based index that includes preoperative C-reactive protein (CRP) and neutrophil-to-lymphocyte ratio (NLR), on therapeutic outcomes for bladder cancer (BC) patients after radical cystectomy (RC)." (PMID 34926263, 2021). "Knowing that CRP is a strong reactive acute phase protein and that CEA may be increased in cases of chronic inflammation and cancer, we can conclude that free light chains are closely related to inflammatory responses during bladder cancer progression." (PMID 37176734, 2023). "As for bladder cancer, a large study on patients with non-muscle-invasive bladder cancer who underwent intravesical bacillus Calmette–Guérin therapy after transurethral resection of bladder tumor looked into CRP and NLR as potential prognostic biomarkers for clinical outcomes." (PMID 39335736, 2024).
head and neck cancer (36 papers, 2010 to 2025). A primary or metastatic malignant neoplasm affecting the head and neck. "CRP has been associated with various cancer types, including lung, breast, colorectal, and head and neck cancers, in numerous studies." (PMID 40565234, 2025). "The study also reported patterns of non-linear associations, including a fast-to-low increase in head and neck cancers, suggesting CRP as a potential biomarker for cancer." (PMID 40565234, 2025). "Previous reports have found that low Hb and high CRP levels were associated with poor prognosis in head and neck cancer." (PMID 37959327, 2023). "Factors independently associated with BSI in patients with head and neck cancer were body temperature (adjusted odds ratio [aOR], 2.563; 95% CI, 1.829–3.593) and C-reactive protein level (aOR, 1.047; 95% CI, 1.009–1.085)." (PMID 36013061, 2022). "Our data indicate that head and neck cancer patients with elevated pre- and post-treatment CRP levels are at higher risk for recurrence of disease, especially residual disease." (PMID 36291945, 2022). "On the other hand, the modified Glasgow Prognostic Score (mGPS), a combination of albumin and the CRP level, was also reported to be associated with cancer cachexia and the prognosis in unresectable locally advanced head and neck cancer patients." (PMID 33531609, 2021). "Many authors have observed an association between elevated serum CRP levels and poor prognosis in cancers such as colorectal, lung, and head and neck cancers." (PMID 32933192, 2020). "We evaluated outcomes over 19 years, including heart inflammations, heart disease, head and neck cancer, C-reactive protein (CRP) levels and overall mortality." (PMID 41420778, 2025). "This meta-analysis explored the prognostic value of the C-reactive protein-to-albumin ratio in head and neck cancers." (PMID 33652976, 2021). "Subgroup analysis showed that the C-reactive protein-to-albumin ratio is a significant prognostic marker for various head and neck cancers." (PMID 33652976, 2021). "An elevated pretreatment C-reactive protein-to-albumin ratio predicts a worse prognosis for patients with head and neck cancers." (PMID 33652976, 2021). "When studying the head and neck cancer treatment toxicity we found that NAG was significantly positively correlated with CRP." (PMID 31420744, 2019). "Recently, the relationship between serum CRP level and head and neck cancer was gradually uncovered." (PMID 29259311, 2017). "For example, a CRP flare defined as a sharp CRP increase in the first weeks after starting treatment, followed by CRP decrease to below baseline, has been associated with ICI treatment response in NSCLC, head and neck cancer, metastatic urothelial carcinoma, and RCC." (PMID 38194216, 2024). "Similarly, some reports have investigated the impact of serum albumin and CRP on the outcome of combination chemoradiotherapy in cases of unresectable head and neck cancers." (PMID 33482792, 2021). "When studying the head and neck cancer treatment toxicity, NAG was observed to increase during RT/CHRT and this increase was correlated with acute radiation-associated toxicity and significantly positively correlated with CRP." (PMID 34208417, 2021). "In addition, if our results are verified, the determination of CRP levels should become standard practice for assessing patients with advanced head and neck carcinoma." (PMID 33201589, 2020). "Based on a stricter serum CRP level (3 mg/L) cutoff, the high-sensitivity mGPS (HS-mGPS) has been reported to be a better prognostic indicator than conventional mGPS for various malignancies, and this superiority was also indicated in a study on head and neck cancer." (PMID 35242712, 2022). "However, the role of the C-reactive protein-to-albumin ratio in other head and neck cancers remains unclear." (PMID 33652976, 2021).
head and neck cancer (continued). "Studies have shown the correlation of survival outcome in patients with head and neck carcinoma with several different inflammation-associated markers such as the neutrophil-to-lymphocyte ratio (NLR), platelet-to-lymphocyte ratio (PLR), and C-reactive protein (CRP)." (PMID 34834580, 2021). "For head and neck cancer, both BM SUV and BML showed significant positive correlations with CRP, NLR, and PLR." (PMID 36354870, 2022). "The prognostic role of CRP in patients with head and neck cancer is not fully understood." (PMID 29259311, 2017).
lupus nephritis (36 papers, 2004 to 2025). Glomerulonephritis in the context of systemic lupus erythematosus. "Anti-CRP antibodies show a resemblance with anti-C1q antibodies, which bind to conformationally altered C1q and are strongly associated with lupus nephritis." (PMID 35690780, 2022). "The aim of the present study was therefore to compare anti-CRP antibody levels in well-characterized lupus nephritis patients and to seek potential associations with histopathology, renal activity and response to therapy." (PMID 20003354, 2009). "This study aimed to evaluate the prognostic value of C-reactive protein-to-lymphocyte ratio (CLR) in lupus nephritis (LN), and compare its utility with neutrophil-to-lymphocyte ratio (NLR) and fibrinogen-to-albumin ratio (FAR)." (PMID 40988967, 2025). "Lupus nephritis, complement 3, immunoglobulin G, serum albumin, C-reactive protein, and hydroxychloroquine were all included in the nomogram model." (PMID 39044159, 2024). "Based on univariate analysis, SLE duration at conception, lupus nephritis (LN), history of therapeutic abortion, C3, lupus anticoagulant, IgG, serum ALB, CRP, PRO, HDL, and HCQ levels were significantly associated with the occurrence of fetal loss." (PMID 39044159, 2024). "CRP staining was observed in the cytoplasm of tubules in 11 of 16 renal biopsies from patients with lupus nephritis (class III: 3; class IV: 6; and class V: 7)." (PMID 37545739, 2023). "CRP was mostly deposited in the renal tubules in patients with lupus nephritis, and the expression of CRP was significantly correlated with tubulointerstitial lesion indices." (PMID 37545739, 2023). "Our staining results showed that CRP was mainly detected in the tubule areas of lupus nephritis patients and patients with autoimmune-related tubulointerstitial nephritis, but was negative in the glomeruli." (PMID 37545739, 2023). "The expression of CRP in lupus nephritis patients was significantly higher than that in the normal controls (P = 0.016)." (PMID 37545739, 2023). "A human proximal tubular epithelial cell line (HK2 cells) was incubated with purified IgG from lupus nephritis, and the production of CRP by HK2 cells was further evaluated." (PMID 37545739, 2023). "A recent phase II double-blind randomized controlled trial showed that anifrolumab can effectively reduce CRP levels in patients with grade III/IV lupus nephritis, but the primary endpoint of the trial (24-hour urine protein to creatinine ratio) was not met." (PMID 36211347, 2022). "Previous studies have found that increased ROS correlates with CRP in lupus nephritis patients, and there is a correlation between inflammatory conditions that trigger oxidation in SLE patients." (PMID 32695177, 2020). "Except anti-dsDNA, autoantibodies against Sm, SSA and SSB, C1q, and C-reactive protein (CRP) have been described in glomerular immune deposits in lupus nephritis patients." (PMID 31783909, 2019). "We have demonstrated a statistically significant correlation between anti-CRP antibody levels and renal biopsy activity index in patients with lupus nephritis." (PMID 20003354, 2009). "Since the present study was limited to patients with lupus nephritis, the prevalence of 45% positive anti-CRP antibody tests was slightly below expectation." (PMID 20003354, 2009). "In this context, very interestingly, the presence of surface-bound CRP has been demonstrated in the renal mesangium and in glomerular capillary walls in specimens from patients with lupus nephritis." (PMID 20003354, 2009). "In the present study, we demonstrate a statistically significant correlation between anti-CRP levels and histopathological activity in lupus nephritis, whereas a baseline positive anti-CRP test predicted poor response to therapy." (PMID 20003354, 2009). "In the present study, we demonstrate a moderate but statistically significant correlation between anti-CRP antibody levels and renal biopsy activity index in lupus nephritis." (PMID 20003354, 2009).
lupus nephritis (continued). "Multivariable linear regression analysis highlighted markers of disease activity such as high CRP, lupus nephritis class III and IV, the presence of U1-RNP antibodies and longer disease duration to be associated with low aBMD, while clinical remission was shown to be beneficial." (PMID 40722203, 2025). "In lupus nephritis higher u-PTX-3 levels were observed in patients with active disease, and in ANCA-associated vasculitis u-PTX-3 seemed to reflect disease activity better than CRP." (PMID 40008348, 2025). "The mean optical density of CRP was significantly correlated with tubulointerstitial lesion indices, such as interstitial inflammatory cell infiltration, tubular atrophy, and interstitial fibrosis in lupus nephritis." (PMID 37545739, 2023). "To verify our hypothesis, we detected CRP expression in renal biopsies from lupus nephritis patients using an immunohistochemistry assay." (PMID 37545739, 2023). "Renal CRP could be produced by tubular epithelial cells after stimulation by lupus nephritis-derived IgG, and the local presence of mCRP might play a critical role in the development of tubulointerstitial lesions." (PMID 37545739, 2023). "Finally, not only the autoantibodies against the unique epitopes of monomeric CRP, but also an autoimmune epitope in lupus nephritis that is exposed only in the monomer are important evidence to support the in vivo generation of monomeric CRP." (PMID 37873776, 2023). "In addition, our research showed that CRP staining in tubules was significantly correlated with urinary mCRP levels in patients with lupus nephritis." (PMID 37545739, 2023). "In addition, there were significantly positive correlations between the expression of CRP in tubules and the levels of urinary mCRP in patients with lupus nephritis (r = 0.550, P = 0.027)." (PMID 37545739, 2023). "Our results showed that these autoantibodies could also induce CRP antigen expression by tubular epithelial cells and might be involved in the progression of lupus nephritis." (PMID 37545739, 2023). "Altered expression of miR-181a was not only observed in SLE and lupus nephritis patients but also correlated to clinical features, such as the erythrocyte sedimentation rate, C reactive protein, anti-dsDNA antibody, complements, and score of SLE disease activity index." (PMID 32382553, 2020). "Previous studies suggest that increased ROS correlates with CRP in lupus nephritis patients." (PMID 32695177, 2020). "A study in Brazil found that increased ROS correlated with CRP in lupus nephritis patients." (PMID 32695177, 2020). "Furthermore, the frequency of CD4+CD45RO+CCR4+ lymphocytes correlated strongly with both ESR and CRP pointing to the potential proinflammatory role of these cells in lupus nephritis." (PMID 29670615, 2018). "However, associations between CRP and individuals with genetically determined lower baseline levels of CRP are at increased risk of SLE and lupus nephritis." (PMID 24167754, 2013). "Salmon's group found CRP deposited in renal glomeruli from patients with lupus nephritis." (PMID 24167754, 2013). "However, we have repeatedly found that anti-CRP levels parallel lupus disease activity, with highest levels in patients with renal involvement; thus, we aimed to study anti-CRP in a material of well-characterized lupus nephritis patients." (PMID 20003354, 2009). "This indicates that anti-CRP could be helpful to assess disease activity and response to therapy in SLE nephritis, and highlights the hypothesis of a pathogenetic role for anti-CRP antibodies in lupus nephritis." (PMID 20003354, 2009). "Given all of these mCRP-mediated biological effects, anti-CRP antibodies may participate in the pathogenesis of lupus nephritis and several mechanisms could be hypothesized." (PMID 20003354, 2009).
lupus nephritis (continued). "In addition, the study suggests that a positive anti-CRP antibody test is superior to anti-dsDNA antibodies and C1q in predicting poor response to therapy in lupus nephritis as judged by renal BILAG." (PMID 20003354, 2009). "In support of this, the expression of the human C-reactive protein, an acute-phase protein closely related to Apcs, has been shown to delay the onset and severity of lupus nephritis in the NZB/W strain by preventing the deposition of immune complexes in the renal cortex." (PMID 15314659, 2004). "Lupus nephritis (LN) was present in 35% of cases, with 61% (23/38) of these being predominantly classified as classes IV and V. Factors significantly associated with lower BMD included LN classes III and IV, U1-RNP antibodies, higher C-reactive protein, and longer disease duration." (PMID 40722203, 2025). "Lupus nephritis-derived IgG could induce CRP production by HK2 cells." (PMID 37545739, 2023). "Although the results of this descriptive study do not allow conclusions regarding nephritogenic properties of anti-CRP antibodies, our data imply that anti-CRP antibody testing is a useful tool to support the clinician's evaluation of disease activity and response to therapy in lupus nephritis." (PMID 20003354, 2009). "Other studies showed significant correlation between IL-6 and SLE, lupus nephritis, SLEDAI scoring, erythrocyte sedimentation rate (ESR), and C-reactive protein to IL-6 expression." (PMID 31697750, 2019). "Lupus nephritis, higher disease activity measured with SLE Disease Activity Index (SLEDAI), and higher levels of CRP have been correlated with impaired brachial endothelial function." (PMID 29435447, 2017). "Additionally, we tested the correlation between CRP and MDA levels in patients with lupus nephritis, lupus musculoskeletal, and lupus cutaneous." (PMID 32695177, 2020). "Similarly, reduced binding of CFH to GAGs and CRP was found to be related to immune damage in SLE and lupus nephritis." (PMID 31861421, 2019). "Interestingly, recent studies indicated that anti-C-reactive protein (CRP) auto-antibodies and anti-PTX3 autoantibodies also correlated with histopathological activity and disease activity in lupus nephritis." (PMID 23510032, 2013). "Thus, the correlations between C1q, CRP, PTX3 and its auto-antibodies in the formation of immune complex in lupus nephritis need further investigation." (PMID 23510032, 2013). "hydroxychloroquine, the SLE activity index (SLEDAI), lupus nephritis, disease duration, C4, ESR, CRP, and C3 did not significantly influence the microbiome composition." (PMID 35477382, 2022). "Compared with patients with noninfectious lupus nephritis, patients with infectious LN had lower levels of red blood cells, hemoglobin, platelets, and lymphocytes (P < 0.01), but a higher proportion of erythrocyte sedimentation rate (ESR) and C-reactive protein (CRP)." (PMID 38649391, 2024).